Y_RNA (Y RNA )
Gene: Miscellaneous RNA gene on chromosome 8 (80,484,589 to 80,484,683, reverse strand). Ensembl gene ENSG00000277604.
Homologues: Orthologues: chimpanzee Y_RNA (100% identical), macaque Y_RNA (78% identical), mouse Gm56181 (52% identical). Paralogues in human: Y_RNA (80% identical), Y_RNA (79% identical), RNY1 (76% identical), RNY1P5 (76% identical), Y_RNA (76% identical), Y_RNA (75% identical), Y_RNA (74% identical), RNY1P2 (73% identical), Y_RNA (73% identical), Y_RNA (72% identical), RNY1P1 (71% identical), Y_RNA (71% identical), and 86 more.